DNMT1 (DNA methyltransferase 1)
Diseases named in the same sentence as DNMT1 in open-access papers (continued):
Sharing a sentence is not in itself a finding about the gene and the disease.
prostate carcinoma (continued). "MS-275, TSA, and VPA downregulate DNMT1 protein expression in testis and embryonal carcinoma, as butyrate, SAHA, and PD98059 do in LNCaP prostate cancer cells." (PMID 26697020, 2015). "We assessed the effects of SFN and DIM on the expression of DNMT1, DNMT3A, and DNMT3B in normal prostate epithelial cells (PrEC), androgen-dependent (LnCAP) and androgen-independent (PC3) prostate cancer cells." (PMID 24466240, 2014). "The degradation of DNMT1 and DNMT3B prompts the demethylation of the promoter of the silenced tumour suppressor gene RASSF1A, leading to the restoration of its expression in prostate cancer cells." (PMID 24001151, 2013). "DNMT1 and HDAC1 levels are upregulated in prostate cancer, suggesting that they play roles in the inactivation of various critical genes via DNA methylation-induced chromatin remodeling." (PMID 24391925, 2013). "Taken together, we show that mahanine treatment induces the proteasomal degradation of DNMT1 and DNMT3B via the inactivation of Akt, which facilitates the demethylation of the RASSF1A promoter and restores its expression in prostate cancer cells." (PMID 24001151, 2013). "We assessed the effects of SFN on the expressions of DNMTs (DNMT1, DNMT3a, and DNMT3b) in benign hyperplasia (BPH-1), LnCap and PC3 prostate cancer cells." (PMID 22303414, 2011). "Furthermore, Western blot analysis demonstrated that saffron treatment induced changes in the expression of other key genes (DNMT1, DNMT3b, MBD2, CD44, HDAC3, c-Myc, NF-kB, TNFα, AR, N-RAS, and PTEN) in prostate cancer cells." (PMID 38201944, 2023). "We demonstrated that gDEC depletes DNMT1 from prostate cancer cells to inhibit their proliferation without activating apoptosis but with epithelial changes that decrease migration and invasion in vitro and in vivo murine xenograft models." (PMID 37345101, 2023). "This study suggests that one consequence of DNMT1-targeting by gDEC is the upregulation of epigenetic activating enzymes to contribute to the overall prostate cancer phenotype change and anticancer effect independent of apoptosis." (PMID 37345101, 2023). "In prostate cancer cells, DNMT1 is reduced to promote epithelial–mesenchymal transition (EMT) and conversion to tumour stem cells by promoting PKCα expression, which in turn promotes prostate cancer growth and metastasis." (PMID 36443876, 2022). "Our data clearly indicates that mahanine treatment causes a decline in the levels of DNMT1 and DNMT3B, without affecting the levels of DNMT3A, in both LNCaP and PC3 prostate cancer cells." (PMID 24001151, 2013). "We note that we also found peptides from LBD1 and DNMT1, but further evaluation showed that these proteins did not exhibit as strong a difference in AR-expressing prostate cancer cells, and we therefore concentrated on NFIC and TBX3, which also interacted with FOXA1 in our other RIME experiments." (PMID 35550030, 2022). "Therefore, anti-cancer agents like mahanine which selectively targets DNMT1 and DNMT3B could be beneficial in prostate cancer therapy." (PMID 24001151, 2013). "In sum, gDEC, in addition to directly depleting the corepressor DNMT1, upregulated KMT activating epigenetic enzymes, activating terminal epithelial program activation, and prostate cancer cell cycling exits independent of apoptosis." (PMID 37345101, 2023). "ID4 expressing (LNCaP) and non-expressing (DU145 and C81) prostate cancer cell lines were used to investigate EZH2, H3K27me3 and DNMT1 enrichment on ID4 promoter by Chromatin immuno-precipitation (ChIP)." (PMID 25115397, 2014). "We show that mahanine induces the degradation of DNMT1 and DNMT3B via the ubiquitin-proteasome mediated pathway in both androgen-responsive LNCaP and androgen receptor-negative PC3 human prostate cancer cells." (PMID 24001151, 2013).
prostate carcinoma (continued). "They found that MH treatment could play a key role in down-regulating DNMT1 and DNMT3B in prostate cancer cells, but not DNMT3A, via the ubiquitin-proteasome mechanism, particularly, the inactivation of Akt that mediates demethylation of the RASSF1A promoter." (PMID 34835969, 2021).
glioma (92 papers, 2010 to 2025). A benign or malignant brain and spinal cord tumor that arises from glial cells (astrocytes, oligodendrocytes, ependymal cells). "Our study revealed that the expression level of NUP37 affects the proliferation and invasion of glioma cells, and that the overexpression of DNMT1 can alleviate the adverse effects caused by NUP37 depletion." (PMID 39174498, 2024). "Further studies were performed, and we found that the enrichment of miR-21 in GA-MSCs exosomes was caused by the miR-21/SP1/DNMT1 positive feedback loop triggered by glioma exosomal CD44." (PMID 37481646, 2023). "In many tumor cells, including glioma cells, high methylation of tumor-suppressor genes and abnormal cell proliferation and apoptosis are associated with increased DNMT1 activity." (PMID 32226508, 2020). "A recent study has reported that phosphorylation of DNMT1 is associated with a global DNA hypomethylation and a poor prognosis in gliomas." (PMID 21619587, 2011). "In parallel with these results, western blot realized from chromatin extraction revealed that the decrease of mMTase activity, seen in glioma, is associated with the decrease of the Dnmt1 quantity recruited on DNA." (PMID 20613874, 2010). "Collectively, all our data identified the disruption of the Dnmt1/PCNA/UHRF1 interactions as a molecular event associated with the degree of global DNA hypomethylation in glial/glioma cells." (PMID 20613874, 2010). "In the present article, we report that Akt overexpression and diuron exposure promote the glioma formation from neural progenitor cells via the induction of DNA hypomethylation mediated by two distinct pathways: the loss of DNMT1/PCNA/UHRF1 interactions and the APOBEC3γ overexpression." (PMID 31727122, 2019). "To test this hypothesis, we looked at the association between DNMT1 expression and DNA methylation in low-grade and high-grade glioma samples from TCGA." (PMID 28036297, 2017). "We analyzed DNMT1 expression and patient survival data in tumors collected from Freiburg and from TCGA and found that DNMT1 was associated with improved patient outcome when gliomas from different tumor grades were included (p-value=1.1E-4)." (PMID 28036297, 2017). "Furthermore, the expression of DNMT1 decreased gradually in both premature and replicative senescent human embryonic lung fibroblasts, and DNMT1 knockdown caused telomere shortening in glioma cell lines." (PMID 28380423, 2017). "This study involved longitudinal analysis samples of primary and recurrent gliomas to determine whether the progression of low- and high-grade gliomas is associated with the promoter methylation of the DNMT1, MGMT and EGFR genes by PCR-based restriction enzyme assay." (PMID 22264301, 2012). "In this manner, NEAT1 functioned as an inhibitory factor on mTOR, thereby facilitating glioma tumorigenesis through the miR‐185‐5p/DNMT1/mTOR signalling pathway." (PMID 40387409, 2025). "So, DNMT1 silencing triggers miR‐152 upregulation, and there is a negative correlation between miR‐152 expression and the presence of DNMT in glioma cell lines." (PMID 40387409, 2025). "In summary, DNMT1 facilitated chemosensitivity by attenuating methylation levels in the promoter region of miR‐20a within glioma cells." (PMID 40387409, 2025). "In this manner, the cellular processes of glioma, specifically cell proliferation and apoptosis, are under the regulatory influence of miR‐152 in conjunction with Runx2, and DNMT1 is critically involved in miR‐152 hypermethylation and downregulation." (PMID 40387409, 2025). "explored the potential correlation between the DNMT1/miR‐20a axis and the sensitivity of glioma cells to temozolomide (TMZ)." (PMID 40387409, 2025). "Conversely, overexpression of DNMT1 led to a significant increase in the methylation rate of CpG sites within glioma cells." (PMID 39174498, 2024). "In conclusion, our study underscored the significance of NUP37 and DNMT1 in the regulation of glioma proliferation." (PMID 39174498, 2024).
glioma (continued). "Collectively, these findings revealed the role of NUP37 in fostering the proliferation, invasion, and migration of glioma cells, primarily via its interaction with DNMT1." (PMID 39174498, 2024). "We found an elevated expression of DNMT1 in both low-grade and high-grade gliomas when compared to normal brain tissue." (PMID 39174498, 2024). "Integrating these findings with previous sequencing data and cellular functional assays, we proposed that NUP37 depletion induced DNMT1 downregulation, thus inhibiting glioma cell proliferation and invasion." (PMID 39174498, 2024). "Correlational analysis of glioma data from the TCGA database demonstrated a positive association between the expression levels of NUP37 and DNMT1." (PMID 39174498, 2024). "In the present study, we conducted an in-depth examination of the expression levels of NUP37 and DNMT1 in gliomas." (PMID 39174498, 2024). "The western blotting analysis indicated that DNMT1 was substantially overexpressed in glioma tissue relative to normal brain tissue." (PMID 39174498, 2024). "In the present study, bioinformatics analysis was performed using DNMT1 co-expressed genes in glioma." (PMID 39174498, 2024). "Taken together, these data indicate that D2HG’s effects on DNMT1 and IRF3/7 that render IDH1mut glioma cells susceptible to virus infection." (PMID 37880243, 2023). "First, knockdown of DNMT1 dramatically inhibited the replication of VSVΔ51 in glioma cells expressing IDH1(R132H)." (PMID 37880243, 2023). "Mechanistically, D2HG produced by mutant IDH1 enhances the binding of DNMT1 to IRF3/7 promoters such that IRF3/7 are downregulated, leading to impaired type I IFN response in glioma cells, which enhances the susceptibility of gliomas to viral infection." (PMID 37880243, 2023). "In summary, we elucidated that GA-MSCs play a key role in promoting the formation of an immunosuppressive glioma microenvironment by amplifying glioma exosomal immunosuppressive signaling through the miR-21/SP1/DNMT1 positive feedback loop." (PMID 37481646, 2023). "In glioma cells, residual HIGD1A levels are maintained separately from HIF induction, and linked to the activity of the DNA methyl transferase-1 (DNMT1) on HIGD1A HREs." (PMID 37686461, 2023). "An example is that DNMT1-regulated lncRNA ADAMTS9-AS2 can be used as a possible biomarker for glioma." (PMID 35109842, 2022). "The nuclear translocation of DNMT1 was decreased in CD133+ glioma cells compared to CD133‐ glioma cells." (PMID 35798319, 2022). "have shown that promoter methylation regulates ADAMTS9‐AS2 expression by knocking down DNMT1 in glioma cells." (PMID 30959550, 2019). "S127 and S143 phosphorylations mediated by PKC (protein kinase C) and AKT (also called PKB, protein kinase B) were observed in glioma and provoked the disruption of DNMT1/PCNA/UHRF1 complex and a consecutive global DNA hypomethylation." (PMID 29449903, 2018). "Our findings indicate that the mRNA levels of UHRF1 and DNMT1 were reduced in glioma cell lines treated with Rhaponticum carthamoides TR extract." (PMID 30171426, 2018).
glioma (continued). "The mRNA levels of UHRF1 and DNMT1 were found to be reduced in both glioma cell lines treated with Rc TR extract." (PMID 30171426, 2018). "CFP1−/− ES cells, showed a reduction of 70% of DNA methylation in single copy genes while a specific inhibition of DNMT1/CFP1 interaction strongly decreased tumor growth of glioma cells in nude mice." (PMID 29449903, 2018). "Downregulation of DNMT1 is also an important finding since it has been shown that its silencing enhances glioma chemosensitivity to temodal." (PMID 29228563, 2017). "Activation of p-c-Jun in a primary mesenchymal cell line leads to increased DNMT1 expression and attenuates the aggressive features of glioma cells." (PMID 28036297, 2017). "ADAMTS9-AS2, a novel tumour suppressor, was modulated by DNMT1 and subsequently contributed to glioma development." (PMID 28764788, 2017). "In conclusion, our results suggest that miRNA-152-3p functions as a novel regulator to promote glioma cells invasion via DNMT1-mediated downregulation of NF2 and can potentially be used as a treatment for GBM." (PMID 28764788, 2017). "Here, we demonstrate that DNMT1 expression is higher in low-grade gliomas compared to glioblastomas and correlates with phosphorylated c-Jun." (PMID 28036297, 2017). "Our analysis of p-c-Jun and DNMT1 expression in clinical glioma biopsy tissues from TCGA highlighted a good correlation between p-c-Jun and DNMT1, supporting previous results in nasopharyngeal carcinoma indicating a role of p-c-Jun in DNMT1 regulation." (PMID 28036297, 2017). "To study the role of DNMTs in gliomas, we used q-RT PCR to analyze the expression of the three DNA methyltransferase enzymes (DNMT1, DNMT3A and DNMT3B) in a panel of low and high-grade gliomas (n=32) collected at the University Medical Center Freiburg." (PMID 28036297, 2017). "Meanwhile, EZH2 was shown to suppress lncRNA SPRY4-IT1 expression in the NSCLC cells, and DNMT1-mediated DNA methylation was found to lead to MEG3 silencing in gliomas." (PMID 28209205, 2017). "Here, we provide evidence for the first time that c-Jun N-terminal phosphorylation regulates DNMT1 expression in lower grade gliomas and proneural glioblastoma and promotes a global gene methylation profile similar to the G-CIMP phenotype." (PMID 28036297, 2017). "Our data suggest the existence of a c-Jun/DNMT1 pathway that functions as a regulator of global methylation in gliomas." (PMID 28036297, 2017). "Our data indicate that increased levels of c-Jun phosphorylation and subsequent induction of DNMT1 expression are responsible for the G-CIMP/proneural phenotype of glioma and adverse to the mesenchymal phenotype." (PMID 28036297, 2017). "This suggests that p-c-Jun causes global methylation changes in glioblastoma and low-grade gliomas similar to those of G-CIMP by regulating DNMT1 expression." (PMID 28036297, 2017). "In summary, we have demonstrated that phosphorylated c-Jun directly binds to and activates the DNMT1 gene promoter and represents a novel regulatory module of genome-wide methylation status in glioblastoma and low-grade gliomas." (PMID 28036297, 2017). "DNMT1 knockdown with RNAi in U251 and U87 glioma cells ameliorated miR-141 methylation, and restored miR-141 mRNA expression." (PMID 27121316, 2016). "Further, we explored the molecular mechanism by which miR-141 expression was regulated, and found that the miR-141 promoter was hypermethylated and that promoter methylation of miR-141 was mediated by DNMT1 in glioma cells." (PMID 27121316, 2016). "From these studies, we propose that DNMT1 downregulation leading to TMZ resistance in glioma cells results in the demethylation of the miR-20a promoter, thereby causing the promotion of miR-20a expression and the development of chemoresistance." (PMID 26337869, 2015). "In summary, DNMT1 mediated chemosensitivity by reducing methylation of the microRNA-20a promoter in glioma cells." (PMID 26337869, 2015).